BMI1 (BMI1 proto-oncogene, polycomb ring finger)
Diseases named in the same sentence as BMI1 in open-access papers (continued):
Sharing a sentence is not in itself a finding about the gene and the disease.
tumor (continued). "Moreover, since BMI1 appears to be a crucial transcription factor regulated by Gli1, having shown that BMI1 inhibitors can control thyroid CSC self-renewal, BMI1 inhibitors should be further evaluated for their inhibitory activity on tumor growth and metastasis." (PMID 33499351, 2021). "Furthermore, BMI-1 and CCNG2 levels evolved inversely during CML progression, suggesting that BMI-1 could support acute transformation of CML through the silencing of a CCNG2-mediated tumor-suppressive autophagy response." (PMID 29466292, 2018). "However, whether Bmi1 marks cells that are competent for prostate regeneration and tumour initiation in intact tissues in vivo has not been examined." (PMID 27703144, 2016). "Interestingly, the tumor cells were found to express Bmi1, AFP and albumin, but not CK19." (PMID 26926789, 2016). "Furthermore, increased expression of EZH2 and BMI1 results in additional downregulation of miR-200 members, which leads to the subsequent upregulation of EMT-promoting transcription factors and favors the invasive behavior of the tumor cells and the progression into MIBC." (PMID 26517683, 2015). "Although genetic depletion of Bmi1 has been described to result in tumor inhibitory effects partly through INK4A/Arf mediated senescence and apoptosis and also through INK4A/Arf independent effects, it has not been proven that Bmi1 can be causally involved in the formation of these tumors." (PMID 22574128, 2012). "Since both Mel-18 and Bmi-1 may play a role in renewal of stem cells, deregulation of these proteins may be one of the initial steps in development of neoplasia and may be present even in non-cancerous tissue adjacent to the tumor tissue." (PMID 21162745, 2010). "Therefore the absence of Bmi1 did not affect the process of tumor initiation." (PMID 19156217, 2009). "Similarly, tumours negative for both, p16 and p14ARF, exhibit moderate–strong bmi-1 staining." (PMID 11355949, 2001). "PTEN, a tumor suppressor that inhibits the PI3K/AKT survival pathway, had a higher level of expression when BMI1 was silenced, irrespective of hyperoxia exposure, evidencing the pivotal role of BMI1 in cell survival and proliferation." (PMID 35431986, 2022). "Bmi-1 is uniquely expressed in head and neck CSC (as opposed to bulk tumor cells), and we showed that this effect is enhanced by IL-6 signaling." (PMID 34689150, 2021). "Altogether, our work supports that BMI1 and RNF2 bear a critical influence on the integrities of replication fork and CFSs, and emphasizes their tumor suppressive, rather than the often-perceived oncogenic, roles." (PMID 32142505, 2020). "Consistent with the previous studies, we showed knockdown of miR-218 expression in non-CSCs induced self-renewal, tumor cell motility and invasion in OSCC, while knockdown of Bmi1 effectively reversed these phenomena." (PMID 27926533, 2017). "RBM24 was significantly downregulated in the tumor tissues and NPC cells compared with the non-tumor tissues and immortalized NPEC1 Bmi-1 cells, respectively." (PMID 27584791, 2016). "The abrogation of Bmi1 expression in the BXB23 and BXB11 background did not yield a significant reduction in tumor initiation events as defined by the number of tumors that were formed in the various genetic combinations by two weeks of age." (PMID 19156217, 2009). "The initial number of tumors in BXB11 versus Bmi1−/−BXB11 however, does not show a significant reduction in Bmi1−/−BXB11 lungs, indicating that the specification of tumor initiating cells does not depend on Bmi1." (PMID 19156217, 2009). "Bmi1 ablation via crossing the Bmi1−/− background into the BXB23 and BXB11 founder line revealed that Bmi1 is not required for tumor initiation but for expansion of initiated cells." (PMID 19156217, 2009). "Particularly, Bmi-1, PSP, SHH, OCT4 and Snail were only expressed on CD133 positive cells; none of the five genes were detectable on CD133 negative tumor cells." (PMID 17140455, 2006).
tumor (continued). "Our data also suggest that Bmi1 levels, rather than RNF2 levels, may be better suited for assessment of gemcitabine efficacy in patients’ tumor specimens." (PMID 24614341, 2014). "At this stage, only lipogenic hepatocytes could be observed in the liver with no tumor lesions, similar to the phenotype observed in AKT/Ras injected Bmi1−/− mice at 8 weeks post injection." (PMID 23029524, 2012).
infection (19 papers, 2005 to 2025). The state of being infected such as from the introduction of a foreign agent such as serum, vaccine, antigenic substance or organism. "RAW264.7 cells were pretreated with active vitamin D and Bmi1 inhibitor (PTC-209) followed infection." (PMID 35957979, 2022). "To explore the effect of senescent fibroblasts on the adjacent vascular smooth cells, we collected the supernatant of fibroblasts with adv-Bmi-1 infection or si-Bmi-1 transfection following by hypoxia treatment for 96 h." (PMID 33673825, 2021). "Following infection, the transduced cells were selected for puromycin resistance for 24 hours, subcultured into 24-well plates, and probed for Nrf2, Sox2, BMI-1 and Cyclin E by immunocytochemistry." (PMID 23937621, 2013). "To determine whether BMI1 was involved in the reduced proliferative capacity of DM1 cells, we overexpressed it in control and DM1 fibroblasts, via lentiviral infection of a construct encoding the full length of the BMI1 sequence." (PMID 36040809, 2022). "Our results revealed that Ad-Bmi-1i selectively silenced Bmi-1 expression in Bmi-1 relatively high-expressed cells, and Bmi-1 silence by Ad-Bmi-1i infection not only induced senescence and inhibited proliferation of GC cells in vitro and in vivo, but also decreased stem-like properties of GC cells." (PMID 27009837, 2016). "Also, at 3 days post-infection, the endogenous Bmi-1 expression level was decreased by 83 and 85%, respectively, in NHOK and SCC4 cells infected with LV-Bmi-1i if compared with the cells infected with LV-GFP." (PMID 17179983, 2007). "Western blot results revealed that the expression of SIRT4, and a panel of stem cell-related molecules including ABCG2, BMI1, and NANOG was significantly suppressed in Hep-12 cells following infection with lentiviruses harboring SIRT4 shRNAs." (PMID 40384857, 2025). "Infection with ST decreased the proliferation genes PCNA, Ki67, and Cyclin; the ISC marker gene Lgr5; the quiescent ISC marker gene Bmi1; the Goblet cell marker gene Muc2; the Paneth cell marker gene Lyz1; and Wnt3a mRNA levels (p < 0.05)." (PMID 38540864, 2024). "OCSCC cells with stable knockdown of BMI1 and ITGB1 were constructed by lentiviral infection and co-cultured with CAF-EVs, respectively." (PMID 38254031, 2024). "To determine whether the observed, infection-dependent, increase in PcG immunofluorescence could be explained by an overall increase in protein expression, we next performed western blot analysis for the PRC2 proteins EZH2 and SUZ12 as well as the PRC1 proteins BMI1 and RING1B." (PMID 22279536, 2012).
adenocarcinoma (8 papers, 2012 to 2021). A common cancer characterized by the presence of malignant glandular cells. "Therefore, BMI‐1 induced HOXC13 repression may cause abnormal cell proliferation contributing to adenocarcinoma." (PMID 27506447, 2016). "A significant number of PanIN lesions (with moderate to severe dysplasia) and adenocarcinoma sections stained for both cytoplasmic and nuclear Bmi1." (PMID 23437065, 2013). "We previously reported a key role for the oncogene BMI-1 in adenocarcinomas." (PMID 33854168, 2021). "Interestingly, Bmi1 staining was predominately expressed in the dysplastic glandular tissue of both PanIN and adenocarcinoma samples, with much less pronounced staining detected in a subset of cells in the stromal component of the neoplastic samples." (PMID 23437065, 2013). "However, the percentage and intensity of high Bmi-1 expression were significantly increased following the progression from columnar cell metaplasia to adenocarcinoma." (PMID 23078618, 2012). "Regarding the results of our study and the literature, the CSCs ALDH1, BMI-1, CD44, Nanog, and SOX2 seem not to serve as reliable prognostic parameters in adenocarcinomas of the salivary glands." (PMID 33009929, 2021). "Recapitulating the results of our study in conjunction with data in the literature, the CSCs ALDH1, BMI-1, CD44, Nanog, and SOX2 do not seem to serve as reliable prognostic parameters in the treatment of adenocarcinoma of the salivary glands." (PMID 33009929, 2021).
hematologic malignancies (7 papers, 2012 to 2024). "Given its substrate targets (e.g. BAF155 and RUNX1) and gene targets (e.g. BMI-1 and ID2), CARM1 and phospho-CARM1 appear to play a pivotal role in hematologic malignancies with the JAK2-V617F mutation, and likely in other settings as well." (PMID 38649367, 2024). "Interestingly, BMI1 is a known biomarker of hematologic malignancies and has been shown to be essential for faithful reprogramming of myeloid progenitors." (PMID 32615918, 2020). "Therefore, our work clearly demonstrates that BMI1 protein can be present in several hematological malignancies, but that only in CD26+ cells (thus CML LSCs) it is co-expressed with the BCR-ABL1 fusion protein." (PMID 30574454, 2018).
prostate (4 papers, 2019 to 2026). "The increases in SCr, BUN, and UAL along with reduced SCrCl seen with Bmi1 knockout indicate development of kidney dysfunction, which correlates with human renal aging." (PMID 38617548, 2024).
degenerative diseases (3 papers, 2012 to 2018). "These evidence indicate that dysregulation of the Bmi-1/p16Ink4a pathway likely plays important roles in provoking the aging-associated decline of stem or progenitor cell function and subsequent onset of degenerative diseases." (PMID 25832744, 2015). "It is clear that these aging-associated degenerative diseases cannot only be explained by our finding of dysregulation of the Bmi-1/p16Ink4a pathway because the loss of p16Ink4a only partially rescued some of the anomalies in Bmi-1-KO SMGs." (PMID 25832744, 2015). "Therefore, dysregulation of the Bmi-1/p16Ink4a pathway is considered key to the loss of tissue homeostasis and development of associated degenerative diseases during aging." (PMID 25832744, 2015). "Thus, better understanding of the downstream mediators of the Bmi-1 pathway will likely facilitate the development of new strategies for prevention or intervention of aging-associated degenerative diseases." (PMID 25832744, 2015). "All together, these findings link important stem cell regulators like Bmi1/Usp16 and Cdkn2a to Wnt signaling, and have implications for designing therapies for conditions, like DS, aging or degenerative diseases, where the Wnt pathway is hampered." (PMID 30504774, 2018). "Therefore, the aging-associated decline of Bmi-1 function may lead to failure of adult stem cell homeostasis and subsequent aging-associated disruption of tissue repair mechanisms and subsequent onset of degenerative diseases." (PMID 25832744, 2015). "Taken together, our work suggests that targeted pharmaceutical stimulation of Bmi1 expression in aging neurons could prevent accumulation of age-associated oxidative damages, protect against apoptosis and possibly counteract the progression of neurodegenerative diseases." (PMID 22384090, 2012). "Bmi-1, a PcG epigenetic regulator that blocks expression of the p16Ink4a CDK inhibitor, plays a key role in aging, and dysregulation of the Bmi-1/p16Ink4a pathway is believed to cause failure of adult stem cell homeostasis and the onset of aging-associated degenerative diseases." (PMID 25832744, 2015).
hematologic cancers (1 paper, 2014). "Expression of Bmi-1 is upregulated in many solid and hematologic cancers." (PMID 25148045, 2014).
intestinal diseases (1 paper, 2021). "We also observed that p16 deletion could ameliorate the microbiota dysbiosis and decrease the inflammation level in Bmi-1–deficient mice, which provides potential targets for the treatment of age-associated intestinal diseases and intestinal microbiota dysfunction." (PMID 34712655, 2021).
BMI1 also shares sentences with these, for which no sentence is quoted: multiple myeloma (8 papers); acute lung injury (2); acute lymphoblastic leukemia (2); alveolar rhabdomyosarcoma (2); Barrett esophagus (2); bladder urothelial carcinoma (2); chondrosarcoma (2); dilated cardiomyopathy (2); endometrial adenocarcinoma (2); esophagogastric junction adenocarcinoma (2); gastrointestinal tumor (2); head and neck tumor (2); mesenchymal tumors (2); metastasis (2); oligodendroglial tumours (2); Parkinson disease (2); schizophrenia (2); testicular cancer (2); acute leukemia (1); acute myocardial infarction (1); acute respiratory distress syndrome (1); Alpha-thalassemia (1); Anxiety (1); arteriosclerosis (1); Arthritis (1); atherosclerosis (1); bacterial infection (1); basal cell carcinoma (1); benign cystadenomas (1); benign neoplasm (1).
A further 79 diseases each share a sentence with BMI1 in 1 paper.